DLX1 (distal-less homeobox 1)
Diseases named in the same sentence as DLX1 in open-access papers (continued):
Sharing a sentence is not in itself a finding about the gene and the disease.
lung adenocarcinoma (1 paper, 2024). A carcinoma that arises from the lung and is characterized by the presence of malignant glandular epithelial cells. "ROC analyses partially indicate that DLX1 is a good predictive biomarker for differentiating lung adenocarcinoma from normal tissue." (PMID 38317839, 2024). "The biological function of distal-less homeobox 1 (DLX1) in lung adenocarcinoma (LUAD) remains unclear, despite a growing body of evidence that DLX1 is involved in the initiation and progression of various tumors." (PMID 38317839, 2024).
lung carcinoma (1 paper, 2024). "The results showed that the upregulation of DLX1 levels was associated with poor clinical outcomes in lung cancer patients." (PMID 38317839, 2024). "The results confirmed that DLX1 was significantly up-regulated in lung cancer cell lines, specifically H1299 and A549 cells." (PMID 38317839, 2024).
lymph node metastasis (1 paper, 2019). "The results found that the expression levels of DLX1 and miR‐539 were not statistically related to age and family history of patients with PCa (P > 0.05), but were associated with lymph node metastasis, pathological stages, tumour size and Gleason scores of PCa (P < 0.05)." (PMID 31298493, 2019).
melanoma (1 paper, 2022). A malignant, usually aggressive tumor composed of atypical, neoplastic melanocytes. "miR-489-3p acts as an anti-oncogenic miRNA by attenuating the expression of distal-less homeobox 1, which shows pro-tumor effects; miR-489-3p can inhibit the proliferation, migration, and migration of melanoma cells by inhibiting SIX1." (PMID 35184643, 2022).
myelodysplastic syndrome (1 paper, 2021). A clonal hematopoietic disorder characterized by dysplasia and ineffective hematopoiesis in one or more of the hematopoietic cell lines. "Aberrant DLX gene expression has been shown for both DLX1 and DLX2 in T-ALL, AML and myelodysplastic syndrome (MDS) patients, showing divergent regulation in the malignant context." (PMID 34829904, 2021).
neuroblastoma (1 paper, 2023). Neuroblastoma (NB) is the most common solid, extracranial childhood tumor. "Although there are no studies available elucidating the expression and function of DLX1 in neuroblastoma, a possible role in the regulation of neural crest cell differentiation mechanisms cannot be excluded, given its expression in neural crest cells." (PMID 37835497, 2023). "Hence, DLX1 is tagged by MYCN binding, a profile that mechanistically is in line with its transcriptional upregulation in MYCN-amplified neuroblastoma cells." (PMID 37835497, 2023).
Obesity (1 paper, 2018). Accumulation of substantial excess body fat. "This obesity phenotype, along with increased AgRP expression in the hypothalamus, suggests that Dlx1/2cKO mice may take more food and/or comsume less energy." (PMID 29795232, 2018). "Dlx1/2cKO mice also showed a reduced energy expenditure as monitored by oxygen consumption and carbon dioxide production, as well as a significantly decreased locomotor activity, both of which were likely reflected in a late-onset obesity." (PMID 29795232, 2018).
psychosis (1 paper, 2010). "Expression of both Dlx1/2 and MR-GEF is retained in both adult mouse and human forebrain where, in human, decreased Dlx1 expression has been associated with psychosis." (PMID 20436929, 2010). "Little is known about Dlx expression in adult human brain; however, decreased Dlx1 expression in the thalamic mediodorsal nucleus, the principal source of thalamic afferents to the cortex that synapse on both pyramidal neurons and interneurons, has been associated with psychosis." (PMID 20436929, 2010). "Both mr-gef and Dlx1 expression is retained in adult mouse and human brain, where Dlx1 has been shown to be decreased in individuals with psychosis." (PMID 20436929, 2010). "In humans, decreased Dlx1 expression in the mediodorsal thalamic nucleus, the principal source of thalamocortical connections that selectively terminate in layers III and IV of the PFC, is associated with psychosis." (PMID 20436929, 2010).
tumor (18 papers, 2011 to 2024). "According to the data from the bioinformatics system StarBase, DLX1 mRNA was suggested as a potential target of tumor-associated miR-4429." (PMID 33740948, 2021). "The results showed that DLX1 expression was significantly higher in tumor tissues compared to normal tissues (p < 0.05)." (PMID 38317839, 2024). "This study provides important information for understanding the function of DLX1, which can be used as a prognostic marker for tumor progression and immune cell infiltration in LUAD." (PMID 38317839, 2024). "DLX1 expression in different malignant tumor types was analyzed using the TCGA database, followed by paired difference analysis." (PMID 38317839, 2024). "While DSC1 gene expression in tumor tissues followed the same pattern as in normal bladder tissues, DLX1 expression was the reverse." (PMID 37876438, 2023). "A wilcoxon rank test reveals significant difference between the blood and tumor tissues for DLX1 (0.005) and DSC1 (0.02734) genes." (PMID 37876438, 2023). "A risk score was generated for each tumor sample with the expression score of GNLY, DSC1, and DLX1, and patients were categorized into two subtypes as high risk and low-risk groups." (PMID 37876438, 2023). "Contrary to the usual normal bladder tissue to blood ratio, DLX1 expression was lower (p = 0.02734) in tumor tissues than in blood." (PMID 37876438, 2023). "In this article, we confirmed that miR-4429 plays a tumor-suppressive role in PCa via mediating DLX1 and Wnt/β-catenin pathway." (PMID 33740948, 2021). "Four weeks post-injection, X-ray scans were taken and subsequently, excised tibia implanted with tumor cells were subjected to micro-computed tomography (microCT), which showed higher bone loss in the control 22RV1-SCR group compared to DLX1-KO." (PMID 34493733, 2021). "The sensitivity of detecting Ta tumor was also superior to the reported methylation assays by DLX1 and ITGA4 (50.0–84.6%) and BCL2, CDKN2A and NID2 (61.1%)." (PMID 33902700, 2021). "Gene-body canyon hypermethylation of DLX1 and its aberrant overexpression were widely observed in four tumor types including BLCA, LUAD, LUSC, and UCEC." (PMID 30097071, 2018). "The expression of DLX1 was significantly different between two groups and correlated with high tumor content, with p- values of 0.018." (PMID 27196083, 2016). "However, the relationship between DLX1 expression, tumor prognosis, and immune infiltration has remained unclear." (PMID 38317839, 2024). "Based on the validation of the prognostic value of DLX1 in different subgroups, we further determined the prognostic value of DLX1 in different clinical subgroups, namely pathological stage, tumor lymph node metastasis (TNM) stage, gender, age, race, smoking status, and smoking age." (PMID 38317839, 2024). "Two additional TFs, TRERF1 and DLX1 were inferred to be more active in tumor than normal tissue." (PMID 37843125, 2023). "Moreover, reduced tumor-sphere forming ability of VCaP cells treated with drug combination group was corroborated by robust decrease in DLX1 expression compared to JQ1 alone." (PMID 34493733, 2021). "In conclusion, miR‐539 overexpression or DLX1 silencing could result in the suppression of tumour growth rate in nude mice." (PMID 31298493, 2019). "Our findings show the complexity and vitality of these tumours, shedding some light on features such their richness in connective tissue and, they point to some interesting candidate genes (i.e., DLX1, DLX2) worth further investigations that could help the pathologists in the differential diagnosis." (PMID 23947815, 2013). "Indeed, the high expression of FOXM1 in numerous cancer cell lines and a variety of tumors is always associated with tumor initiation, development, invasion, metastases and poor prognosis by directly potentiating the expression of tumor-related genes, such as ERα, TOPO-2α, c-Myc, DLX1 and PDGF-A." (PMID 39060421, 2024).
tumor (continued). "The expression of the four target genes (MDGA2, DLX1, DSC1, and GNLY) was investigated in tumor tissues and paired blood samples from 10 BLCA patients who were enrolled in the current study." (PMID 37876438, 2023). "After using the Livak method and normalizing with the ACTB gene, it was found that DLX1 and DSC1 expression was lower in tumor tissues than in blood tissues." (PMID 37876438, 2023). "Subsequently, to investigate the effect of these drugs in the tumor xenografts, we performed IHC staining for cell proliferative marker Ki-67, ALDH1A1, and RNA-ISH for DLX1 expression." (PMID 34493733, 2021). "Similar to DLX1, another m-homeobox gene POU3F3 has hypermethylation canyon in gene-body and aberrant overexpression in multiple tumor types including BLCA, LUSC, and UCEC." (PMID 30097071, 2018). "We revealed TFs whose expression is linked to a large number of tumor-specific enhancers and further characterized selected TFs for each tumor type (e.g., BRCA: GATA3, FOXA1, ESR1, PRAD: HOXC6, DLX1, KIRC: ZNF395) and for specific tumor subgroups." (PMID 27833659, 2016). "Our study demonstrated that the relationship between DLX1 expression and tumor immune cell infiltration was mostly negative." (PMID 38317839, 2024). "Furthermore, DLX1 was found in the top ten upregulated genes in TCGA-PRAD dataset, which harbor tumor-specific ARBS in the neighboring 50 kb region." (PMID 34493733, 2021). "To examine the role of DLX1 in tumorigenesis, we performed mice xenograft experiment by implanting 22RV1-DLX1-KO or 22RV1-SCR control cells subcutaneously in the flank region of immunodeficient NOD/SCID mice and monitored the animals for tumor growth." (PMID 34493733, 2021). "Moreover, a significant decrease in the expression of DLX1 target, ALDH1A1 was also recorded in DLX1-KO tumor tissues." (PMID 34493733, 2021). "Moreover, DLX1 level alone gradually increased as a function of disease stage; ~37% positive in GS6 disease to ~67% positive in GS9 disease, similarly, ~51% in pT2c (pathologic tumor 2c) to 69% in pT3b stage." (PMID 34493733, 2021). "Moreover, the up‐regulation of miR‐539 or DLX1 gene silencing led to the inhibition of PCa cell proliferation, migration, invasion, EMT and tumour growth, accompanied by increased E‐cadherin expression and decreased expression of vimentin, Smad4, c‐Myc, Snail1 and SLUG." (PMID 31298493, 2019).
cancer (13 papers, 2009 to 2025). A tumor composed of atypical neoplastic, often pleomorphic cells that invade other tissues. "The association of DLX1 with the development of malignant tumors has been confirmed in several studies." (PMID 38317839, 2024). "The deregulated DLX gene family members DLX1/2/3/4/5/6 (DLXs) caused by DNA methylation has been demonstrated in various cancers with therapeutic target value." (PMID 32508046, 2020). "We also determined that DLX1 expression in pan-cancer paired cancer tissues and adjacent normal tissues by means of the TCGA dataset." (PMID 38317839, 2024). "This study analyzed DLX1 expression levels in various cancers, including LUAD, from the Cancer Genome Atlas (TCGA) database." (PMID 38317839, 2024). "DLX1 levels were significantly higher in 12 of the 18 cancers compared to normal tissues (p < 0.05)." (PMID 38317839, 2024). "DLX1 in humans exerts crucial roles in the assembly of craniofacial structures, and its dysregulation is engaged in distinct types of cancer." (PMID 37835497, 2023). "Conversely, 22RV1-DLX1-KO and DLX1-silenced VCaP cells showed reduction in the ALDH activity, indicating a plausible function of DLX1 in promoting cancer stemness." (PMID 34493733, 2021). "Together, these data highlight the possible role of DLX1 in promoting cancer stemness, EMT, and proliferation in PCa." (PMID 34493733, 2021). "The locus‐specific hypermethylation of oncogenic homeobox gene DLX1 gene‐body canyon can upregulate its gene expression by pan‐cancer analysis." (PMID 32508046, 2020). "Immunohistochemistry verification of DLX1 gene expression levels with anti-DLX1 showed protein expression was localized to the cancer cell nuclei." (PMID 20021671, 2009). "Furthermore, an increase in the phospho-Akt (pAkt) levels was observed in RWPE1-DLX1 cells, indicating the critical role of DLX1 in regulating cancer cell survival and proliferation." (PMID 34493733, 2021). "Furthermore, DLX1 has been validated as a PCa biomarker across clinically independent cancer cohorts, wherein DLX1 and HOXC6 accurately predict high-grade disease." (PMID 34493733, 2021). "Similarly in other clinical genomics datasets (GSE3598819 and GSE8060920) an increased expression of DLX1 transcript was observed in advanced stage aggressive cancers compared to benign." (PMID 34493733, 2021). "An altered methylation status of some genes is associated with the initiation, growth, and progression of various cancers, and site-specific hypermethylation of the gene body canyon without DLX1, but not the promoter, can directly increase its gene expression." (PMID 38317839, 2024). "Subsequent gene set enrichment analysis (GSEA) showed enrichment of genes involved in the apoptotic pathway in DLX1-KO cells, whereas gene sets involved in epithelial-to-mesenchymal transition (EMT), cancer stemness, active Akt, and Wnt signaling were enriched in the control cells." (PMID 34493733, 2021). "All of our eight candidate genes showed statistically significantly different expression between normal/benign prostate and malignant PCa sample groups, low versus high Gleason grade tumors (PLA2G7), PSA relapse versus no relapse (SPON2), and low versus high TNM stages (CACNA1D and DLX1)." (PMID 27196083, 2016). "The up-regulation and down-regulation of genes in the cancer cells could also be attributed to the activation of specific transcription factors such as ATF3, RUNX2, ERG, DLX1 (and DLX2) identified in the cancer cell transcriptomes." (PMID 20021671, 2009). "DLX1 has no reported role in CCRCC, however, it has a known oncogenic role in other cancer types such as prostate and ovarian cancers." (PMID 37843125, 2023).
neurodevelopmental disorder (2 papers, 2019 to 2025). A behavioral and cognitive disorder with onset during the developmental period that involves impaired or aberrant development of intellectual, motor, or social functions. "Mutations of these deleted genes have not been implicated in a neurodevelopmental disorder in prior work, although common variation at DLX1 and DLX2 has been associated with increased risk of ASD." (PMID 29463886, 2019).
infection (1 paper, 2018). The state of being infected such as from the introduction of a foreign agent such as serum, vaccine, antigenic substance or organism. "Moreover, infection-induced immune cross-reactions might have functional, spatial, and temporal implications related to the functions and expression patterns of DLX1 and DLX5 in the fetal and adult human brain." (PMID 29618965, 2018).
DLX1 also shares sentences with these, for which no sentence is quoted: alcoholism (1 paper); bone tumors (1); brain tumors (1); breast tumors (1); chronic lymphatic leukemia (1); dental fluorosis (1); endometriosis (1); ependymoma (1); Focal cortical dysplasia (1); glioma (1); Kallmann syndrome (1); kidney tumors (1); myopia (1); neurodegenerative disease (1); neurological disorders (1); pancreatic cancer (1); papillary thyroid cancer (1); psychiatric disorder (1).